CD33 (CD33 molecule)
Diseases named in the same sentence as CD33 in open-access papers (continued):
Sharing a sentence is not in itself a finding about the gene and the disease.
Autoimmunity (2 papers, 2016 to 2019). The occurrence of an immune reaction against the organism's own cells or tissues. "On the contrary, immune activation and immune dysfunction lead to increased CD33+CD11b+HLA-DR+ cells, which promote the development of autoimmunity in a nonspecific way." (PMID 27082567, 2016). "Notably, CD33+CD11b+HLA-DR+ cells displayed the same role in HIV patients and healthy controls, which suggest that CD33+CD11b+HLA-DR+ cells contribute to the development of autoimmunity in a nonspecific way." (PMID 27082567, 2016).
bipolar disorder (2 papers, 2020 to 2024). A disorder of the brain that causes unusual shifts in mood, energy, activity levels and the ability to carry out day-to-day tasks. "Two CEACAM5-specific antibodies and one bi-specific CEA/CD33 antibody with no prior connections to bipolar disorder were also identified using WDD and Open Targets." (PMID 32398742, 2020).
chronic periodontitis (2 papers, 2020 to 2024). A chronic inflammatory process that affects the tissues that surround and support the teeth. "Heterogeneous staining was observed in each periodontitis specimen with an overall elevation for MDSC markers, CD11b+ and CD33+, compared with the healthy gingiva." (PMID 31685946, 2020). "However, our finding that 2/8 periodontitis specimens from noncancer patients had elevated CD11b+/CD33+ MDSC, suggested that its infiltration can be an inherent feature of periodontitis, rather than tumor progression." (PMID 31685946, 2020).
cutaneous melanoma (2 papers, 2020 to 2022). A primary melanoma arising from atypical melanocytes in the skin. "Survival amongst patients with skin cutaneous melanoma was associated with high CD33 expression in the TCGA cohort." (PMID 35493454, 2022). "Consistent with previous data that VISTA is mainly expressed on hematopoietic cells and myeloid cells, and not exhausted or activated T cells, our study showed that VISTA expression correlated with the expression of the MDSC marker CD33 in cutaneous melanoma." (PMID 32873829, 2020). "Moreover, CD33 expression correlated with PD-1 expression, which suggests the possibility that PD-1 expression could be affected by CD33-positive MDSCs in cutaneous melanoma." (PMID 32873829, 2020). "Multivariate analysis showed that both CD33 and VISTA expression were independent prognostic factors in cutaneous melanoma." (PMID 32873829, 2020). "The expression of CD33+ MDSCs in cutaneous melanoma and its relationship with PD-1 expression has not been evaluated." (PMID 32873829, 2020).
esophageal cancer (2 papers, 2018 to 2021). A primary or metastatic malignant neoplasm involving the esophagus. "Circulating CD33+ MDSCs were independently associated with decreased survival in various cancer types including esophageal cancer." (PMID 30285868, 2018).
Hepatic fibrosis (2 papers, 2021 to 2022). The presence of excessive fibrous connective tissue in the liver. "An increase in hepatic CD11b+CD33+ MDSCs positively correlated with liver fibrosis and also linearly correlated with the tumor volume." (PMID 35720398, 2022). "In particular, we found that the expression of CD11b+CD33+ MDSCs was positively correlated with AFP and hepatic fibrosis in patients with HCC." (PMID 33860040, 2021). "Ultimately, the present study suggests that hepatic CD11b+CD33+ MDSCs are increased in HCC and AIH and positively correlate with the liver stages of hepatitis activity and liver fibrosis stage." (PMID 33860040, 2021). "Taken together, the CD11b+CD33+ MDSC level is correlated with the biochemical parameters of CLD patients, including the degree of liver fibrosis and enzymes related to liver injury, indicating that the level of MDSCs may be associated with disease progression." (PMID 33860040, 2021).
Hepatitis (2 papers, 2021 to 2025). Inflammation of the liver. "Our data also suggest that inflammation severity may modulate the cognitive effects in hepatitis patients with specific CD33 SNPs." (PMID 40637125, 2025). "This could explain the impact of CD33 SNPs on the cognitive profiles seen in our hepatitis cohorts." (PMID 40637125, 2025).
hypospadias (2 papers, 2020). Hypospadias is the displacement of the urethral meatus on the ventrum of the penis. "This region on chromosome 19 is characterized by clusters of sialic acid-binding Ig-like lectin (SIGLEC) and kallikrein (KLK) genes, among which we identified likely causal relationships with hypospadias (CD33/SIGLEC3, SIGLEC5, SIGLEC7, KLK5, KLK7, KLK10, KLK13, and KLK14)." (PMID 32728162, 2020).
influenza (2 papers, 2023 to 2024). An acute viral infection of the respiratory tract, occurring in isolated cases, in epidemics, or in pandemics; it is caused by serologically different strains of viruses (influenzaviruses) designated A, B, and C, has a 3-day incubation period, and usually lasts for 3 to 10 days. "The phylum Defluviitaleaceae and the genus Defluviitaleaceae mediated 10.46% and 10.91% of their influenza protective effect by upregulating CD33+ HLA DR+ CD14- %CD33+ HLA DR+ cells." (PMID 39062949, 2024). "Rhesus macaque CD33+ myloid cells showed effects on T cell inhibitory functions and these cells were also transiently increased after vaccination with influenza mRNA vaccine." (PMID 37179166, 2023).
metastatic cancer (2 papers, 2021 to 2026). A carcinoma which has spread from the original site of growth to another anatomic site. "Myeloid features and markers (CD163, CD33, CD68 etc.)can be seen in metastatic cancer cells." (PMID 34257573, 2021).
monocytic leukemia (2 papers, 2024 to 2025). "Morphologically, bone marrow often exhibits features of granulomonocytic or monocytic leukemia, while immunophenotypically, there is frequently high expression of CD33, low expression of CD13, and negativity for CD34 and HLA-DR." (PMID 39432585, 2024).
Myelodysplasia (2 papers, 2020 to 2022). Clonal hematopoietic stem cell disorders characterized by dysplasia (ineffective production) in one or more hematopoietic cell lineages, leading to anemia and cytopenia. "For example, midostaurin is added to target FLT3-ITD/TKD mutations; gemtuzumab ozogamicin (GO) is added to target the high expression of CD33; and CPX351 is added to target AML with myelodysplasia-related changes (AML-MRC)." (PMID 36181538, 2022).
T-cell leukemia (2 papers, 2020 to 2021). A malignant disease of the T-lymphocytes in the bone marrow, thymus, and/or blood. "For instance, the aberrant expression of myeloid markers such as CD13 and CD33 has been detected in precursor T-cell leukemias which may presage a poor prognosis in comparison with T-cell leukemia cases without the expression of myeloid antigens." (PMID 34620233, 2021).
triple-negative breast carcinoma (2 papers, 2021 to 2023). An invasive breast carcinoma which is negative for expression of estrogen receptor (ER), progesterone receptor (PR), and human epidermal growth factor receptor 2 (HER2). "Controversially, recent evidence has shown that increased CD33+ myeloid cells were associated with better prognosis in triple negative breast cancer." (PMID 33920514, 2021).
type 2 diabetes (2 papers, 2012 to 2015). "Although diverse mechanisms have been proposed to explain the increase of inflammatory cytokines in patients with type 2 diabetes, to our knowledge, this is the first study to describe an association between CD33 and the inflammatory cytokine profile in type 2 diabetes patients." (PMID 22500980, 2012). "A significant decrease in the cell surface expression of CD33 was detected in monocytes obtained from patients with type 2 diabetes, as compared to those from healthy volunteers (P < 0.05)." (PMID 22500980, 2012). "CD33 expression was significantly decreased in monocytes from patients with type 2 diabetes, and higher levels of TNF-α, IL-8 and IL-12p70 were detected in the plasma of patients compared to healthy donors." (PMID 22500980, 2012). "The primary finding of our study is that CD33 cell surface protein and mRNA expression levels are significantly reduced in monocytes from patients with type 2 diabetes." (PMID 22500980, 2012). "Additionally, from patients with type 2 diabetes, the levels of CD33 expression on freshly obtained monocytes and serum cytokine levels were evaluated and compared to those from healthy individuals." (PMID 22500980, 2012). "Therefore, we studied CD33 expression and inflammatory cytokine secretion in freshly isolated monocytes from patients with type 2 diabetes." (PMID 22500980, 2012). "In addition, CD33 mRNA expression was also reduced in monocytes from type 2 diabetes patients." (PMID 22500980, 2012). "Because CD33 is a regulator of cytokine production, these findings suggest that low levels of CD33 expression could be involved in the elevated inflammatory cytokine production observed in patients with type 2 diabetes." (PMID 22500980, 2012).
acute megakaryoblastic leukemia (1 paper, 2023). Acute megakaryoblastic leukemia (AMKL) is a form of acute myeloid leukemia (AML) that occurs predominantly in childhood and particularly in children with Down syndrome (DS-AMKL). "In acute megakaryoblastic leukemia (AMKL), blasts express MK/PLT lineage antigens and myeloid antigens (CD13/CD33)." (PMID 37729123, 2023).
acute myelomonocytic leukemia (1 paper, 2023). "Immunophenotyping by flow cytometry of BM aspirate revealed a blast cell population including 15% myeloblasts (CD34+, HLADR+, CD13+, CD33+, and CD38+) and 25% promonocytes (CD64+, CD13+, CD33+, HLADR+, and aberrant expression of CD56), a profile compatible with acute myelomonocytic leukemia." (PMID 37841434, 2023).
Apathy (1 paper, 2025). Apathy is a quantitative reduction of interest, motivation and the initiation and persistence of goal-directed behavior, where often the accompanying emotions, thoughts, and social interactions are also diminished. "Composite apathy scores were strongly and positively correlated with mRNA fold changes for all examined genes: Tyrobp, Trem2, C1qa, C1qb, C1qc, C3, C3ar1, and Cd33 (p < 0.0001)." (PMID 41377997, 2025).
basophilic leukemia (1 paper, 2024). "Besides, the role of CD33 on basophils in the transition from MDS to basophilic leukemia is noteworthy." (PMID 38819469, 2024).
biliary tract cancer (1 paper, 2024). "Basophil %CD33dim HLA DR- CD66b- (OR=0.91, 95% CI=0.84–1.00, P=0.038) and CD33 on CD33br HLA DR+ (OR=0.95, 95% CI=0.90–1.00, P=0.04) from the myeloid lineage showed a negative correlation with biliary tract cancer risk, indicating an association with a decreased risk of biliary tract cancer." (PMID 39050844, 2024).
bipolar I disorder (1 paper, 2024). A bipolar disorder that is characterized by at least one manic or mixed episode. "Empirical evidence suggests that the percentages of CD11b/CD33+ hi and CD11b/CD33+ lo cells differed significantly between T carriers and healthy controls in patients with bipolar I disorder in the Han Chinese population." (PMID 39220183, 2024).
bladder cancer (1 paper, 2025). "In bladder cancer, CD33+ MDSCs are significantly elevated in the tumor mass, primarily as eMDSCs (CD33+DR-CD15-CD14-)." (PMID 40136652, 2025).
blood disease (1 paper, 2023). A disease that occurs in the blood. "Composite flow cytometric data for human CD45 and CD33 demonstrated decreased peripheral blood disease in AQ-treated mice (p < 0.0001 by ANOVA)." (PMID 36831684, 2023).
breast tumor (1 paper, 2023). "Furthermore, we examined the expressions of CD33 and CD15 in 31 breast tumor samples by immunohistochemistry (IHC) and found staining scores of these two PMN-MDSC markers were much higher in CCL20high-expressing tumors than in CCL20low-expressing tumors." (PMID 36859354, 2023).
Cholecystitis (1 paper, 2025). The presence of inflammatory changes in the gallbladder. "Our TSMR approach demonstrated that glycine levels act as mediators in the association between CD45 on CD33 br HLA-DR+ cell and cholecystitis." (PMID 40991677, 2025). "As CD45 on CD33 br HLA-DR+ increased, as did the risk of cholecystitis." (PMID 40991677, 2025).
cutaneous squamous cell carcinoma (1 paper, 2022). "Consistently, CD147 was found overexpressed in cutaneous squamous cell carcinoma (cSCC), and positively related with the expression of CD33, a myeloid-associated marker." (PMID 35964097, 2022).
dysgerminoma (1 paper, 2020). A malignant germ cell tumor characterized by the presence of a monotonous primitive germ cell population. "BM examination of the osteolytic lesions revealed multifocal, dense infiltrates of mast cells that showed positive immunohistochemical staining for mast cell tryptase, CD25, CD33, and c-KIT, but no dysgerminoma cell was observed." (PMID 33246418, 2020).
dysplasia (1 paper, 2015). A usually neoplastic transformation of the cell, associated with altered architectural tissue patterns. "Here, we examined the number of MDSCs in HPV 16 infection with normal oral mucous specimens, dysplasia, caner in situ and oropharyngeal cancer using the PE-Cy mouse anti-human CD11b, FITC- mouse anti-human LIN, APC mouse anti-human HLA-DR, PE mouse anti-human CD33." (PMID 26193368, 2015).
epilepsy (1 paper, 2026). A brain disorder characterized by episodes of abnormally increased neuronal discharge resulting in transient episodes of sensory or motor neurological dysfunction, or psychic dysfunction. "Administration of a CD33 agonist (monosialoganglioside 1, GM1), a negative moderator of TREM2 that reduces its levels, attenuated microglial phagocytosis of inhibitory synapses and weakened susceptibility to epilepsy and seizures." (PMID 41965330, 2026).
Ewing tumor (1 paper, 2024). "In summary, these collective results demonstrate that NOA2 treatment of humanized mice bearing Ewing tumors leads to the recruitment of CD33+ monocytes/myeloid cells." (PMID 38534214, 2024). "In vivo treatment of Ewing tumor-bearing mice with NOA2 results in a tumoral infiltrate of morphologically activated mouse CD14+ cells and an increase in human CD33+ cells." (PMID 38534214, 2024).
gastric tumor (1 paper, 2013). "A higher density of CD33+/p-STAT1+ cells was inversely related to infiltrating CD8+ T lymphocytes but not B cells, supporting that CD33+/p-STAT1+ cell might be a subset of MDSCs in gastric tumor tissue." (PMID 23307253, 2013).
graft versus host disease (1 paper, 2025). An immune system disorder that occurs after allogeneic hematopoietic stem cell transplant and is a reaction of donor immune cells against host tissues. "After the infusion of CD33 CAR-NK cells, no immune effector cell–associated neurotoxicity syndrome (ICANS) or graft-versus-host disease (GVHD) was observed." (PMID 39748428, 2025).
Graves disease (1 paper, 2024). Graves' disease is an autoimmune disorder that leads to overactivity of the thyroid gland (hyperthyroidism).It is caused by an abnormal immune system response that causes the thyroid gland to produce too much thyroid hormones. "Most notably, Actinobacteria (p) presented protective effects on Hashimoto’s thyroiditis via CCR2 on myeloid Dendritic Cell (5.0%), and Bifidobacterium (g) showed facilitating effects on Graves’ disease through CD39+ CD4+ T cell %CD4+ T cell (5.0%) and CD14 on CD33+ HLA DR+ CD14dim (12.2%)." (PMID 39351300, 2024).
HCMV infection (1 paper, 2005). "Further studies of HCMV infection in CD34 cells will help in defining whether CD34+ infected cells undergo cell differentiation by increased expression of other markers such as CD33, CD38, HLA-DR or cytokines." (PMID 15673469, 2005).
Hyperbilirubinemia (1 paper, 2016). An increased amount of bilirubin in the blood. "Additionally, only a transient hyperbilirubinemia within 2 weeks of CAR.CD33 T-cell infusion was observed in this patient." (PMID 27907031, 2016).
idiopathic pulmonary fibrosis (1 paper, 2025). Idiopathic pulmonary fibrosis (IPF) is a nonneoplastic pulmonary disease that is characterized by the formation of scar tissue within the lungs in the absence of any known cause. "Bidirectional Mendelian randomization analysis revealed an inverse association between the Cd33+ monocyte subset and the risk of idiopathic pulmonary fibrosis." (PMID 41007655, 2025).
intrahepatic cholangiocarcinoma (1 paper, 2024). A carcinoma that arises from the intrahepatic bile duct epithelium in any site of the intrahepatic biliary tree. "In a desmoplastic intrahepatic cholangiocarcinoma (ICC) mouse model, cancer-associated fibroblasts (CAFs) recruited CD33+ MDSCs to the tumor and also mediated hyperactivation of 5LO metabolism in the MDSCs through CAF-derived IL-6 and IL-33." (PMID 38786066, 2024).
kidney tumors (1 paper, 2022). "Lin, CD11b, CD33, and CD44 were hypomethylated, while CD55 was hypermethylated in RMCs compared to the other kidney tumors." (PMID 36291828, 2022).
leukocytosis (1 paper, 2016). "In this patient, the diagnosis of de novo AML with mutated NPM1 was made on his first bone marrow biopsy showing 70% CD13, CD33, CD117, HLA-DR(+), and CD34(−) myeloblasts with circulating blasts and marked leukocytosis." (PMID 27752371, 2016).
leukopenia (1 paper, 2025). "Additionally, a study on CD33-targeted CAR-T-cell therapy for AML demonstrated a transient reduction in CD33+ leukemic blasts (lasting only 7 days), accompanied by adverse effects such as leukopenia." (PMID 40008144, 2025).
liver cancer (1 paper, 2022). An epithelial or non-epithelial malignant neoplasm that arises from the liver. "We found that LAIR1 expression was generally highly correlated with CD33 (a marker for myeloid cells) and CD4 (a marker for T cells) in most cancers except liver cancer." (PMID 36211388, 2022).
liver neoplasm (1 paper, 2024). Tumors or cancers of the LIVER. "Furthermore, Progeni predicted the sialic acid binding Ig-like lectin 3 (SIGLEC-3, or CD33) protein with the second-highest prediction score for liver neoplasms." (PMID 38578805, 2024).
lymph node metastasis (1 paper, 2020). "The infiltration of CD33+ cells was positively associated with T stage, pathological grade, lymph node metastasis and poor prognosis." (PMID 32092078, 2020).
lymphoid leukemia (1 paper, 2024). A malignant lymphocytic neoplasm of B-cell or T-cell lineage involving primarily the bone marrow and the peripheral blood. "CD33 on CD33dim HLA DR- mediated the causal relationship between Retinol to oleoyl-linoleoyl-glycerol (18:1 to 18:2) ratio and lymphoid leukaemia (Mediated proportion = -13%[-23.5%, -2.55%])." (PMID 39351228, 2024). "CD33 on Im MDSC mediated the causal relationship between Retinol to oleoyl-linoleoyl-glycerol (18:1 to 18:2) ratio and lymphoid leukaemia (Mediated proportion = -13.1% [-23.1%,-3.09%])." (PMID 39351228, 2024). "CD33 on Mo MDSC mediated the causal relationship between DHEAS (Mediated proportion = -9.67%[-19.4%,0.025%]), Pregnenolone sulfate (Mediated proportion = -9.2%[-17.4%,-0.965%]), and lymphoid leukaemia." (PMID 39351228, 2024). "CD33 on Gr MDSC mediated the causal relationship between DHEAS (Mediated proportion = -9.56%[-16%,-3.16%]), Androstenediol (3beta,17beta) monosulfate (Mediated proportion = -12.3%[-20.7%, -3.83%]), and lymphoid leukaemia." (PMID 39351228, 2024). "CD33 on CD14+ monocyte mediated the causal relationship between DHEAS (Mediated proportion = -9.72%[-17.8%,-1.65%]), Androstenediol (3beta,17beta) disulfate (Mediated proportion = -14.6% [-26.9%,-2.27%]), and lymphoid leukaemia." (PMID 39351228, 2024).
lymphopenia (1 paper, 2020). Reduction in the number of lymphocytes. "Functional enrichment analysis also highlighted a marked shift in cellular population within the circulation with a significant enrichment for transcriptional profiles associated with CD14 + monocytes and CD33 + myeloid cells, underscoring the lymphopenia observed in COVID19 + ICU patients." (PMID 33306162, 2020).